TRIM21 (tripartite motif containing 21)
Diseases named in the same sentence as TRIM21 in open-access papers (continued):
Sharing a sentence is not in itself a finding about the gene and the disease.
colorectal cancer (20 papers, 2018 to 2026). A primary or metastatic malignant neoplasm that affects the colon or rectum. "Then, we performed IHC to evaluate the potential association between MICALL2 and TRIM21 in the serial sections of human colorectal cancer tissue microarrays." (PMID 36307841, 2022). "Interestingly, TRIM21 is associated with a reduction in stemness and metastatic potential of colorectal cancer (CRC) cells, but also contributes to chemotherapy resistance and tumorigenesis of CRC." (PMID 39890802, 2025). "In colorectal cancer, TRIM21 can directly interact with and ubiquitinate the lysine 473 (K473) site of MST2 via K63 linkages." (PMID 39963114, 2025). "For the first time, we uncovered that TRIM21, a tumor suppressor gene in colorectal cancer, binds to PRMT1 using its SPRY domain and acts as an E3 ubiquitin ligase, promoting the ubiquitination and degradation of the oncogene PRMT1 in a K48-linked manner." (PMID 39890802, 2025). "TRIM21 functions as an inhibitory regulator on the metastatic potential of colorectal cancer by regulating Hippo/YAP signaling pathway." (PMID 40735642, 2025). "To investigate the tumor suppressor effect of TRIM21 in colorectal cancer, we transfected control vector plasmid and TRIM21 overexpression plasmid in HCT-116 cells." (PMID 39890802, 2025). "The staining results consistently supported the database analysis, demonstrating lower TRIM21 expression in colorectal cancer compared to normal tissue." (PMID 39890802, 2025). "Our results also show that upregulation of TRIM21 in HCT116 colorectal cancer cells promotes tumorigenesis in xenografted mice." (PMID 35048968, 2022). "Taken together, we highlighted the vital role of MICALL2, as an E3 ubiquitinase TRIM21 substrate, in colorectal cancer progression by activating Wnt/β-catenin signaling pathway." (PMID 36307841, 2022). "In colorectal cancer cells, TRIM21 interacts with MICALL2 and down-regulates it synergistically via ubiquitination and degradation, and negatively regulates the activities of MICALL2 in CRC." (PMID 36307841, 2022). "Then, the interaction between endogenous MICALL2 and TRIM21 in colorectal cancer cells was validated in the co-immunoprecipitation experiment." (PMID 36307841, 2022). "While the impact of TRIM21 on cancer has been studied in various tumors, its role in colorectal cancer (CRC) remains unclear." (PMID 39890802, 2025). "In colorectal cancer, TRIM21-mediated K63 ubiquitination reduces the stability of the hnRNPA2B1 protein, leading to a decline in nuclear export and translation of KRAS mRNA, and reduced activation of the MAPK signaling pathway, ultimately inhibiting the malignant progression of colorectal cancer." (PMID 40379610, 2025). "In the present study, we found that Tripartite motif containing 21 (TRIM21) was highly expressed in colorectal cancer (CRC) and could be valuable for predicting the prognosis of CRC patients." (PMID 40998798, 2025). "Additionally, our study emphasizes the possibility of developing targeted drugs that specifically activate TRIM21, presenting a promising therapeutic approach for the treatment of colorectal cancer and opening up new avenues for clinical intervention." (PMID 39890802, 2025). "Interestingly, TRIM21 was reported to play a tumor-suppressive role in some cancers (e.g., breast and colorectal cancer), whereas it was reported to promote tumorigenesis in some other cancers (e.g., brain and liver cancer)." (PMID 36749630, 2023). "In addition, TRIM21 binds to PRMT1 via its SPRY domain to promote the ubiquitination and degradation of the oncogene PRMT1 in a K48-linked manner, thereby inhibiting the metastasis of colorectal cancer cells." (PMID 40735642, 2025).
colorectal cancer (continued). "TRIM21 mediates ubiquitination of the Hippo pathway kinase MST2 and reduces colorectal cancer metastasis." (PMID 39543140, 2024). "As a substrate of ubiquitinase TRIM21, MICALL2 enhances the growth and migration of colorectal cancer cells and activates the Wnt/β-catenin signaling pathway." (PMID 36307841, 2022). "To investigate the subcellular distribution of Trim21 and its potential association with mitochondria, we performed immunofluorescence staining using anti-Trim21 antibodies in combination with MitoTracker staining in both SW620 and HT29 colorectal cancer cell lines." (PMID 41274938, 2025). "Compared with matched adjacent nontumor samples, TRIM21 protein levels were downregulated in 63% (n = 57 of 90) and 44% (n = 22 of 50) of two different cohorts of tumor samples, respectively, and in 50% (n = 20 of 40) of a cohort of colorectal cancer samples." (PMID 36749630, 2023). "And, in colorectal cancer tissues, there is a negative correlation of MICALL2 expression level with TRIM21, which promotes the ubiquitination and degradation of MICALL2." (PMID 36307841, 2022). "Furthermore, in those colorectal cancer samples, a negative correlation between MICALL2 and TRIM21 proteins was observed (r = − 0.30, P < 0.01)." (PMID 36307841, 2022).
dermatomyositis (20 papers, 2012 to 2026). Dermatomyositis (DM) is a type of idiopathic inflammatory myopathy characterized by evocative skin lesions and symmetrical proximal muscle weakness. "Also of note, two of 36 patients with polymyositis/dermatomyositis overlap had anti-Jo-1 antibodies (6%), and both of these had anti-Ro52/TRIM21 antibodies." (PMID 22394602, 2012). "In particular, anti-Ro52/TRIM21 antibody-positive patients were significantly more likely to have overlap with polymyositis/dermatomyositis (6% versus 3%; P = 0.0431) compared with anti-Ro52/TRIM21 antibody-negative patients." (PMID 22394602, 2012).
COVID-19 (19 papers, 2020 to 2025). A disease caused by infection with severe acute respiratory syndrome coronavirus 2. "In the context of COVID-19, the literature has demonstrated the role of TRIM21 in promoting the ubiquitination of the SARS-CoV-2 nucleocapsid." (PMID 40141410, 2025). "On the other hand, TRIM21 transcription was significantly higher in myeloid cells collected from patients with mild COVID-19." (PMID 40141410, 2025). "Taken together, our data suggest the participation of TRIM21 in the refined pathophysiology of COVID-19, possibly having a protective role through the degradation of the virus, but leading to no robust inflammation in the lungs." (PMID 40141410, 2025). "Using machine learning, we identified a set of diagnostic plasma biomarkers (e.g., TRIM21, CASP8, PTN and CSF1) that had very high accuracy in differentiating COVID-19 from CAP, and outperformed standard laboratory parameters used in clinical practice." (PMID 36829233, 2023). "Taken together, all pieces of evidence strongly support the involvement of PVRL1, TRIM29, and TRIM21 in COVID-19, but further investigation is warranted." (PMID 36353114, 2022). "Therefore, it is unlikely that the TRIM21 pathway plays a protective role exerted by ILCs in mild cases of COVID-19." (PMID 40141410, 2025). "The increased levels of cytokines, malfunctioning T-cells, and activation of TRIM21 in individuals that are affected by or recovering from COVID-19 may make them more vulnerable to developing oral lichen planus." (PMID 37510944, 2023). "The intracellular neutralisation data generated by the EDNA assay represents an indirect evidence that the TRIM-21 mediated mechanism of immunity could play a relevant role in protection against COVID-19." (PMID 34867975, 2021). "Therefore, reaching an approximate number of lung cells from mild COVID-19 patients who could express TRIM21 and the required components of the pathway would be speculative." (PMID 40141410, 2025). "The E3 protein ligase TRIM21, which is identified in the lamina propria of OLP lesions, is overexpressed in COVID-19 patients and plays a critical role in autoimmune pathologies." (PMID 37510944, 2023). "Nonetheless, most plasma protein biomarkers that were identified with the two ML algorithms outperformed all the clinical variables in differentiating COVID-19 from CAP, with TRIM21 having the highest AUC (C for ROC curves of the remaining proteins)." (PMID 36829233, 2023). "In whole blood study, seven autoantigens were upregulated in blood of severe COVID-19 patients (MPO, PRTN3, PADI4, IFIH1, TRIM21, PTPRN2, and TSHR), while four autoantigens (MPO, PRTN3, IFIH1, and PADI4) were increased in blood of mild patients." (PMID 34276672, 2021). "Finally, through machine learning, we identified biomarkers, such as TRIM21, PTN and CASP8, that accurately differentiated COVID-19 from CAP-sepsis with higher accuracy than standard clinical markers." (PMID 36829233, 2023). "In addition, the plasma proteome alterations identified unique features associated with respective disease, allowing the discovery of potential plasma biomarkers for differential diagnosis of COVID-19 and CAP-sepsis, among them TRIM21, PTN and CASP8." (PMID 36829233, 2023).
scleroderma (19 papers, 2007 to 2025). Scleroderma is a rare autoimmune connective tissue disorder characterized by abnormal hardening of the skin and, sometimes, other organs. "In 2012, the Canadian Scleroderma Multicenter Study Group’s comprehensive analysis of autoantibodies associated with 963 patients with SSc showed that anti-TRIM21 was detected in 20% of patients and was the second most common autoantibody in the patient cohort, except for anti-centromere antibodies." (PMID 39165359, 2024). "Anti-centromere, or none of the tested autoantibodies (anti-TRIM21 included) had numerically lower risks of developing cancer within two years in the cohort of SSc.Anti-Topo I and anti-U1-RNP associated with cancer risk within two years of scleroderma onset." (PMID 39165359, 2024).
pancreatic cancer (15 papers, 2020 to 2025). "Finally, we identified TRIM21 is a pivotal gene linked to pancreatic cancer prognosis and gemcitabine resistance in pancreatic cancer." (PMID 39739616, 2025). "To explore the function of TRIM21 in gemcitabine resistance in PC, we established gemcitabine‐resistant pancreatic cancer cell lines BXPC3‐GR and SW1990‐GR." (PMID 39739616, 2025). "This study integrates multi‐omics to reveal TRIM21's pivotal role in pancreatic cancer development and resistance to gemcitabine." (PMID 39739616, 2025). "To validate the interaction between METTL3 and TRIM21, we transfected pancreatic cancer cells with a Flag-tagged METTL3 expression vector or a vector encoding His-tagged TRIM21." (PMID 40175350, 2025). "Given the critical role of TRIM21 in pancreatic cancer, we conducted a small molecule drug screening using lipid modifying agents to target the binding domain between TRIM21 and EPHX1." (PMID 39739616, 2025). "The CCK‐8 assay demonstrated that TRIM21 silencing attenuated the resistance of pancreatic cancer cells to gemcitabine." (PMID 39739616, 2025). "To investigate its regulatory role, we generated stable TRIM21 knockdown and overexpression pancreatic cancer cell lines." (PMID 40919143, 2025). "Microsomal epoxide hydrolase 1 (EPHX1) metabolizes 2-arachidonoylglycerol (2-AG) into arachidonic acid (AA) and glycerol, and has been identified as a direct target of TRIM21 in pancreatic cancer." (PMID 40735642, 2025). "The E3 ubiquitin ligase TRIM21 mediates proteasomal degradation of METTL3 via K48-linked ubiquitination at residue Lys459, thereby promoting ferroptosis in pancreatic cancer and enhancing antitumour immunity." (PMID 41463025, 2025). "To investigate the role of TRIM21 in pancreatic cancer cells, we established TRIM21‐overexpressing (TRIM21‐OE) cell line models for BXPC3, SW1990, and Pan02, as well as TRIM21‐knockout (TRIM21‐KO) cell line models for SW1990 and PANC1." (PMID 39739616, 2025). "Meanwhile, we found the same results in pancreatic cancer cells, indicating that the E3 ligase activity of TRIM21 is required for METTL3 ubiquitylation." (PMID 40175350, 2025). "In this context, our study identified TRIM21 as a critical driver of pancreatic cancer progression and gemcitabine resistance." (PMID 39739616, 2025). "Compared to the normal pancreatic ductal epithelial cell line HPDE6‐C7, TRIM21 mRNA and protein levels were substantially elevated in pancreatic cancer cell lines." (PMID 39739616, 2025). "We next investigated the effects of TRIM21 promotes ferroptosis by targeting METTL3 as an intervention for pancreatic cancer progression in vivo." (PMID 40175350, 2025). "Our findings demonstrate that hypoxia drives pancreatic tumor progression by downregulating TRIM21, leading to stabilization of the oncogenic protein ID1." (PMID 40919143, 2025). "In vivo, ID1 silencing impeded, while TRIM21 knockdown accelerated, pancreatic tumor growth, confirming their opposing roles in tumor progression." (PMID 40919143, 2025). "It is also demonstrated that high TRIM21/Ro52 expression in pancreatic tumor patients indicates worse survival outcome." (PMID 37993883, 2023). "Notably, the regulatory function of TRIM21 in ferroptosis extends beyond pancreatic cancer and exhibits context-dependent variability." (PMID 41463025, 2025). "TRIM21 acts as a tumor suppressor by promoting ferroptosis in pancreatic cancer, suggesting that targeting the TRIM21-METTL3-SLC7A11 axis may be a novel effective therapeutic strategy for pancreatic cancer." (PMID 40175350, 2025). "However, there is currently few research confirming that METTL3 or TRIM21 regulates the ferroptosis process in pancreatic cancer." (PMID 40175350, 2025). "To understand the functional consequences of this interaction, we first examined whether the expression of TRIM21 affects the METTL3 protein levels in pancreatic cancer cells." (PMID 40175350, 2025).
pancreatic cancer (continued). "IF staining confirmed highest expression of immune checkpoints PD-L1 on TRIM21 overexpression tumors in comparison to other groups, indicating TRIM21 could promote tumor immunogenicity in pancreatic cancer." (PMID 40175350, 2025). "In addition to the known ferroptosis effect caused by the activation of TRIM21-METTL3 axis in tumor cells, in this study, we next validated the consequences of TRIM21-METTL3 mediated ferroptosis on the efficacy of anti PD-1 immunotherapy in pancreatic cancer." (PMID 40175350, 2025). "Additionally, the expression level of TRIM21 increases with the clinical staging and pathological progression of pancreatic cancer." (PMID 39739616, 2025). "By preventing TRIM21‐mediated ubiquitination and subsequent degradation of EPHX1, Bezafibrate sensitizes pancreatic cancer cells to gemcitabine, offering a novel and promising therapeutic strategy." (PMID 39739616, 2025). "More importantly, we demonstrated that inhibiting the interaction between TRIM21 and EPHX1 with Bezafibrate significantly sensitized pancreatic cancer cells to gemcitabine." (PMID 39739616, 2025). "Functionally, EPHX1-derived AA promotes ferroptosis and suppresses tumor proliferation, whereas TRIM21-mediated EPHX1 degradation sustains AA depletion, thereby enhancing pancreatic cancer growth and conferring gemcitabine resistance." (PMID 40735642, 2025). "Considering that TRIM21 functions as an E3 ligase, we analyzed the polyubiquitination of endogenous METTL3, which was further enhanced in pancreatic cancer cells treated with the proteasome inhibitor MG132." (PMID 40175350, 2025). "Taken together, these results revealed that TRIM21 increased PD-L1 expression and significantly enhanced antitumor immunity to impede tumor progression via regulating METTL3 in pancreatic cancer." (PMID 40175350, 2025). "In conclusion, hypoxia-induced downregulation of TRIM21 stabilizes ID1 and promotes pancreatic tumor progression, highlighting the TRIM21–ID1 pathway as a promising therapeutic target for pancreatic adenocarcinoma." (PMID 40919143, 2025). "In pancreatic cancer, CD73 promoted the metastasis of PDAC by binding to the E3 ligase TRIM21, competing with the Snail for its binding site." (PMID 39423241, 2024). "Our finding is supported by recent findings that higher expression of TRIM21 decreases the response to CDDP in colon cancer and pancreatic cancers, and that somehow contributes to chemo-resistant." (PMID 32023548, 2020). "Our study elucidated the precise molecular mechanism of the TRIM21-METTL3 axis in pancreatic cancer and revealed that METTL3 may be a potential target in pancreatic cancer therapy." (PMID 40175350, 2025). "Interestingly, the TRIM21-METTL3 axics mediated ferroptosis effectively increased the expression of immune checkpoint PD-L1 and strengthened antitumor immunity in pancreatic cancer." (PMID 40175350, 2025). "Finally, ubiquitination assays in TRIM21-knockdown cells revealed that TRIM21 ablation significantly attenuated ID1 ubiquitination, supporting its role as a critical E3 ligase for ID1 degradation in pancreatic cancer cells." (PMID 40919143, 2025). "However, transwell and wound healing assays revealed no significant impact of TRIM21‐OE and TRIM21‐KO on pancreatic cancer cell migration." (PMID 39739616, 2025). "Together, our findings first elucidated the detailed molecular mechanism of METTL3 degradation and revealed the pivotal role of the TRIM21-METTL3 axis in regulating ferroptosis and antitumor immunity, which may serve as a potential target for pancreatic cancer treatment." (PMID 40175350, 2025).
rheumatoid arthritis (15 papers, 2012 to 2025). A chronic, systemic autoimmune disorder characterized by inflammation in the synovial membranes and articular surfaces. "Notably, FBXO2 expression is increased in rheumatoid arthritis patients, coinciding with elevated levels of tripartite motif-containing 21 (TRIM21), also known as the SSA/Ro52 antigen." (PMID 40004214, 2025). "Interestingly, TRIM21 has been found as an autoantigen in several autoimmune diseases, including Rheumatoid Arthritis (RA), Systemic Lupus Erythematous (SLE), and Sjogren’s syndrome." (PMID 34943240, 2021). "This study aimed to evaluate the clinical and immunological significance of anti-Ro52/TRIM21 and anti-Ro60/SSA antibodies in rheumatoid arthritis (RA), particularly the association of dual antibody positivity with disease severity, systemic manifestations, and therapeutic resistance." (PMID 40901469, 2025).